IL4 (interleukin 4)
Diseases named in the same sentence as IL4 in open-access papers (continued):
Sharing a sentence is not in itself a finding about the gene and the disease.
asthma (continued). "Furthermore, different studies have shown that Mg2+ can interfere with the activation of NF-κB, a central pathway in the transcription of proinflammatory genes, such as TNF-α, IL-4, IL-5, and IL-13, all of which are implicated in asthma pathophysiology." (PMID 40868515, 2025). "Elevated IL‐4 levels are associated with Th2‐driven inflammation, which is common in asthma." (PMID 41185941, 2025). "Dupilumab, a fully human anti-IL-4 receptor-α monoclonal antibody, blocks IL-4 and IL-13 signaling to downregulate itching-associated cytokines, chemokines, and IgE levels, which has been applied in allergic diseases treatment, i.e., AD and asthma treatment." (PMID 39975679, 2025). "Gene variants encoding immune regulators, such as IL-4 and IL-13, had been linked to an increased chance of developing asthma; these cytokines orchestrate pathways of IgE class switching and Th2 differentiation, driving key pro-inflammatory features within the airway." (PMID 40337626, 2025). "Currently, there is extensive research on asthma susceptibility genes, confirming associations with genes such as interleukin-4 (IL-4), interleukin-13 (IL-13), β2 adrenergic receptor (ADRB2), Zona Pellucida Binding Protein 2 (ZPBP2), and numerous other candidate genes." (PMID 40433469, 2025). "In asthma-susceptible neonatal BALB/c mice, RvE2 reduced eosinophil counts and IL-4, IL-5 and IL-13 levels, suggesting that RvE2 may prevent asthma risk." (PMID 39720728, 2024). "The mechanism by which dupilumab improves asthma control and reduces exacerbation while eosinophils are persistent may be linked to an impact of IL-4 and IL-13 on mucus secretion and airway smooth muscle." (PMID 38291489, 2024). "In addition, asthma conditions have been linked to increased levels of inflammatory cytokines such as IL-4, IL-5, IL-17, IL-13, and TNF-α in addition to decreased IFN-γ and IL-10." (PMID 39295946, 2024). "Although there are observed ethnic differences, IL-4 polymorphisms have been linked to total IgE levels and may also be related to asthma and other allergy-related traits." (PMID 38699097, 2024). "IL-4, together with IL-5 and IL-13, are Type 2 (T2)-high asthma-associated cytokines that are assumed to provide the main asthma manifestations, such as bronchial hyperreactivity, mucus hyperproduction, immunoglobulin E (IgE) synthesis, and airway eosinophilia." (PMID 39767651, 2024). "Interleukin-4 (IL-4) is a secreted cytokine involved in the induction and persistence of the type 2 immune response, which is believed to be associated with atopic diseases such as asthma and atopic dermatitis." (PMID 38339208, 2024). "Interleukin (IL) genes, particularly IL-4 and IL-13, have been linked to asthma pathogenesis." (PMID 38699097, 2024). "Allergic inflammation, which is the pathogenesis of allergic rhinitis and asthma, is associated with disruption of the airway epithelial barrier due to the effects of type 2 inflammatory cytokines, i.e. interleukin-4 and interleukin-13 (IL-4/13)." (PMID 38687777, 2024). "In addition, IL-4 is associated with the increased airway sensitivity that occurs in asthma, leading to increased bronchial constriction when exposed to allergens or other irritants." (PMID 39407835, 2024). "Analysis of the allele frequencies ofthese polymorphic gene variants revealed significant differencesin the rare T allele frequency of IL4 rs2243250 and IL13rs1800925 in children with mild and severe asthma (in thecase of rs1800925) compared with healthy children ( p < 0.05)." (PMID 37465198, 2023). "Both Th1 and Th2 cytokines, including IFN-γ, IL-4, and IL-13 have been shown to induce asthma; however, the underlying mechanisms remain unclear." (PMID 36824812, 2023). "IL-4 induced macro-autophagy in antigen-presenting B cells and is linked to asthma pathophysiology." (PMID 36451006, 2023). "Aberrant Th2-mediated asthma is associated with Th2 cytokines such as IL-4, -5, and -13." (PMID 37569348, 2023).
asthma (continued). "Multiple cytokines, including IFNγ, IL-4, and IL-13 are associated with asthma; however, the mechanisms underlying the effects of these cytokines remain unclear." (PMID 38081868, 2023). "The discovery of the mechanism underlying allergic disease, mouse models of asthma, and bronchoscopy studies provided initial insights into the role of Th2-type cytokines, including interlukin (IL)-4, IL-5 and IL-13, which became the target of monoclonal antibody therapy." (PMID 37259416, 2023). "By compromising the integrity of the sinonasal and bronchial epithelial layers in patients with asthma and nasal polyposis, IL-4 and IL-13 cause a dysfunction of the airway epithelial barriers, thus increasing their permeability to aeroallergens and infectious agents." (PMID 37240477, 2023). "Aberrant production of IL-4 due to genetic mutations or hyperresponsiveness to this cytokine might further contribute to the severity of asthma." (PMID 37063828, 2023). "It has been reported that asthma is associated with a rise in IgE, IL-4, and IL-1β levels." (PMID 37623736, 2023). "Hijazi Z., Haider M.Z. Interleukin-4 gene promoter polymorphism[C590T] and asthma in Kuwaiti Arabs." (PMID 37465198, 2023). "Asthma and AD are frequently associated with atopy and are characterized by elevated levels of type 2 cytokines (IL-4, IL-5, IL-13), which cause IgE production, mast cell activation, and basophil and eosinophil recruitment, well-known cellular actors in IgE-mediated inflammatory response." (PMID 36364420, 2022). "In fact, the level of Th1 cytokines IL-12 and IFN-ɣ as well level of Treg cytokine IL-10 in lung of asthma mice was lower than control, and inversely, Th2 cells response-associated the cytokines IL-4, IL-5, and IL-13 had a significant increase in lung of asthma mice compared to the control group." (PMID 36685604, 2022). "Many published studies found an association between polymorphisms in the IL4 gene and asthma." (PMID 35456412, 2022). "The increase in IL-4 levels among malnourished children could be a risk factor for developing asthma although further research is still needed." (PMID 36143913, 2022). "Notably, IL-4 is a T helper 2 (Th2)-derived interleukin and that Th2 linked inflammatory response is linked to asthma pathogenesis, which is consistent with our KEGG pathway findings." (PMID 36264868, 2022). "This SNP is reported previously with reference ID rs2243290 in studies conducted to find polymorphisms in IL-4 gene which could be associated with various diseases like trypanosomiasis, cancer, asthma and allergy." (PMID 36407356, 2022). "Therefore, we conclude that in our case, DEPs induced T-helper-2-type-associated asthma involving eosinophils, IL-4, and IL-13." (PMID 36293642, 2022). "Therefore, it is important to understand the interactions between IRSs, IL-4, and IL-13 proteins to explore the possible roles implicated in asthma." (PMID 36077511, 2022). "When the Th2 expression is hyperactive, the IL-4 and IL-13 synthesize specific allergen IgE, which binds to the eosinophil/mast cell membrane high-affinity substance and induces the release of inflammatory waterfall that causes asthma." (PMID 35859797, 2022). "Although the assessed inflammation parameters showed significant differences in IL-4 and IL-13, their association with allergic disorders such as asthma suggests that these changes could be driven by factors external to the dietary intervention." (PMID 36235579, 2022). "Interleukin-9 (IL-9)-producing CD4+ T helper cells (Th9) have been implicated in allergy/asthma and anti-tumor immunity, yet molecular insights on their differentiation from activated T cells, driven by IL-4 and transforming growth factor-beta (TGF-β), is still lacking." (PMID 36241625, 2022). "IL-4 and IL-13 are called prototypical type 2 cytokines, which can cause immunoglobulin E (IgE) production and eosinophils can transport to the airways, thus triggering an asthma attacks." (PMID 36530558, 2022).
asthma (continued). "Excessive levels of IL-13, and the functionally related IL-4, are associated with increased allergic responses (Th2 inflammation and asthma) and resistance to parasites; the inclusion of inhibitory receptors of these Th2 molecules in vaccines has augmented immunity to infections such as HIV." (PMID 36060742, 2022). "The inflammatory cascade in severe asthma is mainly caused by T-helper 2 cells (Th-2) activation and the release of Th-2 related cytokines, predominantly Interleukin-4 (IL-4), IL-5, and IL-13.32,34 The extent of expression of these cytokines correlates with asthma severity." (PMID 35414610, 2022). "IL-4 and IL-13 are essential for the induction and persistence of the type 2 immune response, and they are associated with multiple atopic diseases, such as asthma and atopic dermatitis." (PMID 33450900, 2021). "IL-4, IL-5, and IL-13 are type 2 cytokines associated with asthma." (PMID 35111694, 2021). "Both IL-4 and IL-13 cause immunoglobulin class switch to IgE during asthma." (PMID 35386975, 2021). "IL-4 activates B cells to secrete IgE, and IgE binds to mast cells, mast cells activated by IgE can release histamine after re-expose with allergen, which causes allergic and inflammatory responses in asthma patients." (PMID 33884360, 2021). "A hallmark of asthma is elevation in the levels of Th2-type cytokines, such as IL-4 and IL-13." (PMID 34580637, 2021). "Particularly, type 2 (T2)-high asthma is a complex endotype associated with high type 2 inflammatory markers including immunoglobulin E (IgE), interleukins (IL)-4, IL-5, and IL-13, and it is characterized by AHR, eosinophilia, and excessive airway mucus production." (PMID 34572466, 2021). "We further show that IL-4-activated eosinophils shared a transcriptome signature that was similar to eosinophils from Type 2-associated diseases (e.g. asthma) whereas IFN-γ + E. coli-activated eosinophils were similar to eosinophils from a Type 1 associated disease (e.g. colitis)." (PMID 34970274, 2021). "Moreover, quercetin is known to ameliorate the pathogenic process of asthma by decreasing IL-4 and IFN-γ synthesis and by regulating Th1/Th2 balance." (PMID 33668814, 2021). "This type of asthma is called Type 2 (T2) asthma because it is orchestrated by Th2 lymphocytes that secrete a series of interleukins such as IL-4, −5, −9, and −13, which cause activation and recruitment of eosinophils, as well as the generation of IgE by B lymphocytes." (PMID 34276407, 2021). "This suggests that residual cytokine activity in mice vaccinated with kinoids might sustain IgG production, while reducing the pathogenic functions of IL-4 and IL-13 in asthma." (PMID 33976140, 2021). "The binding of IL-33 to its ST2 receptor activates transcription factors, via MyD88 dependent but TRIF independent pathway, and stimulates the production of Th2 cytokines such as IL-4, IL-5 and IL-13 in wild type mice, also restoring the Th2 asthma phenotype in IL-4 deficient mice." (PMID 34324507, 2021). "In addition to their atopic and allergic effects, IL-4, IL-5, IL-9, and IL-13 are strongly implicated in airway inflammation seen in asthma and reactive airway disease." (PMID 35003073, 2021). "In the subgroup analysis by age, the results rejected the significant association between IL-4 C33T polymorphism and risk of asthma in different age groups except for allelic model, which highlighted the predisposing role of the T allele for the asthma risk in all three age groups." (PMID 33228581, 2020). "It was revealed that IL4 gene −589C/T polymorphism increased the risk of asthma across all genetic models, including dominant model (OR = 1.22), recessive model (OR = 1.17), allelic model (OR = 1.21), and TT vs. CC model (OR = 1.34), but not the CT vs. TT model." (PMID 33087044, 2020). "Furthermore, subgroup analysis by age indicated that IL4 gene -589C/T polymorphism was significantly associated with asthma risk in both pediatrics and adults." (PMID 33087044, 2020).
asthma (continued). "In a whole, IL4 gene -589C/T polymorphism increased the risk of asthma across all genetic models." (PMID 33087044, 2020). "This study aimed to identify the correlation between serum levels of ghrelin, obesity, and asthma with the possible role of some associated inflammatory cytokines—particularly IL-4, IL-5 and IL-21—in children to investigate ghrelin as a future target in the management of asthma." (PMID 32143340, 2020). "Finally, the ethnicity-specific analysis disclosed a significant association between IL-4 C33T polymorphism and asthma risk in Caucasians (all genotype models except heterozygote comparison), while this association was not significant in African-Americans." (PMID 33228581, 2020). "A meta-analysis has revealed the association of different single nucleotide polymorphisms (SNPs) in the IL4 gene associated with susceptibility to asthma in Caucasian-European populations, especially the rs2070874 (C-33T) and rs2243250 (C-589T), located in the promotor region." (PMID 32366038, 2020). "It was observed that IL4 gene -589C/T polymorphism increased the risk of asthma across all genetic models, including dominant model (OR = 1.22), recessive model (OR = 1.17), allelic model (OR = 1.21), and TT vs. CC model (OR = 1.34), but not the CT vs. TT model." (PMID 33087044, 2020). "As a consequence, it is a biological justification that IL4 gene −589C/T SNP impresses the IL-4 expression and, hence, could affect the asthma susceptibility." (PMID 33087044, 2020). "Moreover, when tested in association with this IL-4/IL-13 dual receptor antagonist, the anti-asthma actions of such two biologicals were comparable to those exerted by dupilumab alone." (PMID 33329598, 2020). "Additionally, subgroup analysis was conducted according to ethnicity; the results showed a significant association between IL-4 C33T polymorphism and asthma risk in Caucasians under all models except CT vs TT model." (PMID 33228581, 2020). "In the subgroup analysis by age, a significant association between IL-4 C33T polymorphism and risk of asthma in different age groups was identified in allelic model, which highlighted the predisposing role of the T allele for the asthma risk in all three age groups." (PMID 33228581, 2020). "Moreover, the subgroup analysis by age indicated that IL4 gene -589C/T polymorphism was significantly associated with asthma risk in both pediatrics and adults." (PMID 33087044, 2020). "The CpG in the IL4 gene region, cg26787239, which was significantly associated with serum tIgE levels, was also the most significant signal in recent work performed in an asthma cohort." (PMID 31443688, 2019). "This terminology was expanded to another commonly occurring human asthma phenotype, with justification provided for the introduction of an “allergic equine asthma” phenotype associated with a Th-2 predominant response, characterized by increased expression of IL-4 and IL-5 in BAL-derived cells." (PMID 31694631, 2019). "The IL-4 promoter polymorphism is associated with increased total serum IgE, which is of special interest, since this group of cytokines is involved in asthma development and could be influenced during and after RSV infection." (PMID 31572372, 2019). "Asthmatics experimentally infected with rhinovirus had increased viral titres compared to infected healthy controls, with greater airway inflammation, bronchial hyperreactivity, and reductions in lung function associated with increased levels of IL-4, IL-5 and IL-13 in BAL." (PMID 30764493, 2019). "Our results show, for the first time, that such anti-asthma effects may be associated with reduction of the IL-4/JAK1/STAT6 pathway." (PMID 30172259, 2018). "The early finding of the relationship between asthma and the occurrence of Th2 cells and their marker cytokine IL-4 is still a key feature of bronchial asthma and could also be confirmed on the genetic level in association studies on asthma and atopy." (PMID 31826038, 2018).
asthma (continued). "To clarify the underlying mechanism of how IL-4 and/or IL-13 generates asthma-like phenotypes by acting on airway epithelial cells, we studied IL-4/IL-13–inducible genes in those cells using a DNA microarray and found that SCCA1 and SCCA2 are downstream molecules of IL-4/IL-13." (PMID 29642409, 2018). "Similarly, mTOR in patients experiencing asthma was associated with the loss of Th1/Th2 balance, as the level of mTOR in the serum of these patients correlated positively with the level of IL-4 and negatively with the level of IFN-γ." (PMID 28674387, 2017). "High levels of IL-4 and IL-6 and low levels of IL-12 were apparent in asthma patients, while IL-4, IL-6, and IL-12 might be associated with lung function and QOL of asthma patients." (PMID 28328807, 2017). "In our study, IL-4 and IL-13 were positively associated with Easy-to-Control asthma." (PMID 28686637, 2017). "In summary, this study demonstrated that IL-4, IL-6, and IL-12 levels might be associated with the moderate-to-severe asthma of children." (PMID 28328807, 2017). "However, increased systemic and local IL-4 levels are also found in chronic Th2-associated inflammatory conditions such as asthma and AD7–10." (PMID 29203829, 2017). "Considerable evidence indicates that IL-4 from mast cells may be implicated in the pathogenesis of allergic inflammations such as allergy, asthma, and rhinitis." (PMID 28724321, 2017). "The most important characteristic feature of asthma is chronic airway inflammation which is associated with increased number of Th2lymphocytes and their cytokines (IL-4, IL-5, IL-9, and IL-13) while Th1 lymphocytes and their cytokines (IL-2, IFN-γ, and IL-12) are reduced." (PMID 28824424, 2017). "A respiratory allergy such as asthma is predominantly caused by Th2 inflammatory responses in the airway, which are characterized by the induction of Th2 cytokines including IL-4, IL-5, and IL-13 that lead to IgE production, increased mucus production, and eosinophilia." (PMID 28824649, 2017). "Dupilumab, a blocker of both IL-4 and IL-13, may be of utility in asthma and EoE-associated remodeling." (PMID 28831387, 2017). "Consequently, it is believed that IL-4, IL-6, and IL-12 levels in PB were associated with lung function and cellular immune function in children with moderate-to-severe asthma." (PMID 28328807, 2017). "Therefore, excessive cytokines IL-4, IL-5, and IL-13 produced by Th2 cells are significant risk factors in asthma pathogenesis." (PMID 27870920, 2016). "These CD4+ T cells produce various cytokines, namely IL-4, IL-9, and IL-13, that may contribute toward the underlying inflammation in asthma." (PMID 28066445, 2016). "Nonetheless, we find that naive Itk-deficient T cells can differentiate into IL-4 producing cells in vitro, raising the question of whether Itk may affect expression of other cytokines implicated in asthma." (PMID 26936133, 2016). "Interestingly, in mast cells and lung tissue, P2Y6 deficiency will reduce IL-4 expression most obviously in ovalbumin-induced asthma." (PMID 27590515, 2016). "The suppressive effects of ME on PGE2 formation may contribute to its increased antiallergic activity, as PGE2 may mediate asthma development and inflammation associated with IL-4 and IL-5, which are produced by helper T cells." (PMID 25960618, 2015). "We then searched for clinical conditions that could benefit from the same experimental approach using genes associated with the M(IL-4, IL-13) phenotype, such as asthma and pulmonary fibrosis, and constructed another list of genes with the GSEA tool." (PMID 26302899, 2015). "Recent studies have also pointed to a role for private IL4 mutations in African Americans that may be associated with asthma susceptibility." (PMID 26540410, 2015). "Furthermore, presence of the T allele at IL4 rs2227284 has been associated with higher IgE levels in White, African-American, and Hispanic asthma patients." (PMID 26693492, 2015).